SHB (SH2 domain containing adaptor protein B)
Description:
Adapter protein which regulates several signal transduction cascades by linking activated receptors to downstream signaling components. May play a role in angiogenesis by regulating FGFR1, VEGFR2 and PDGFR signaling. May also play a role in T-cell antigen receptor/TCR signaling, interleukin-2 signaling, apoptosis and neuronal cells differentiation by mediating basic-FGF and NGF-induced signaling cascades. May also regulate IRS1 and IRS2 signaling in insulin-producing cells.
Synonyms: bA3J10.2
Tractability: Antibody: UniProt places it where antibodies can reach, with medium confidence; its Gene Ontology location is reachable by antibodies, with medium confidence. PROTAC: UniProt records ubiquitination sites on it; its protein half-life has been measured.
Gene: Protein-coding gene on chromosome 9 (37,915,898 to 38,069,227, reverse strand). Ensembl gene ENSG00000107338.
Subcellular location: Cytoplasm; Cell membrane
Subcellular location (Human Protein Atlas): Cytosol; Cytoplasmic bodies; Nucleoplasm
Pathways (Reactome):
Signal Transduction: VEGFA-VEGFR2 Pathway
Gene Ontology:
Molecular function: phosphotyrosine residue binding; protein binding; signaling receptor complex adaptor activity
Biological process: signal transduction
Cellular component: cytosol; cytoplasm; plasma membrane
Genetic constraint (gnomAD): Loss-of-function variants: 20 observed, 39.26 expected, observed/expected ratio (o/e) 0.51, 90% interval 0.36 to 0.74. The synonymous counts are far from expectation, so gnomAD's model fits this gene poorly and the ratio says little. Missense variants: 825 observed, 617.68 expected, observed/expected ratio (o/e) 1.34, 90% interval 1.26 to 1.41. Synonymous variants: 397 observed, 270.26 expected, observed/expected ratio (o/e) 1.47, 90% interval 1.35 to 1.6.
Homologues: Orthologues: chimpanzee SHB (100% identical), macaque SHB (99% identical), rabbit SHB (98% identical), dog SHB (97% identical), pig SHB (96% identical), rat Shb (93% identical), mouse Shb (93% identical), guinea pig SHB (83% identical), tropical clawed frog shb (66% identical). Paralogues in human: SHF (41% identical), SHD (33% identical), SHE (31% identical).
Diseases named in the same sentence as SHB in open-access papers:
SHB is named in the same sentence as 11 diseases in open-access papers, as found by Europe PMC text mining. Sharing a sentence is not in itself a finding about the gene and the disease. The quoted sentences say what the papers report.
acute myeloid leukemia (1 paper, 2023). Acute myeloid leukemia (AML) is a group of neoplasms arising from precursor cells committed to the myeloid cell-line differentiation. "Concordantly, SHB expression was associated with shorter survival time, co-expression of immune cell and vascular related genes in human Acute Myeloid Leukemia (AML)." (PMID 38028548, 2023).
atopic dermatitis (1 paper, 2019). "When SHB-deficient DCs were inoculated into mice with atopic dermatitis, mice developed more severe disease symptoms." (PMID 31052382, 2019).
fungal infection (1 paper, 2020). "Because we wanted to test how PH impacts ShB resistance, not how ShB resistance impacts PH, it was important to collect PH data in the absence of fungal infection." (PMID 32206941, 2020).
gastric cancer (1 paper, 2022). A primary or metastatic malignant neoplasm involving the stomach. "Examination of gastric cancer samples from the VARIANZ cohort revealed that HAS2 and SHB are predictive risk factors for response to trastuzumab therapy." (PMID 35264144, 2022). "The gene expression analysis in gastric cancer specimens revealed that HAS2 and SHB were predictive risk factors for trastuzumab therapy response." (PMID 35264144, 2022). "Analogue to HAS2, SHB gene expression was analyzed in gastric cancer specimens." (PMID 35264144, 2022).
Graves disease (1 paper, 2024). Graves' disease is an autoimmune disorder that leads to overactivity of the thyroid gland (hyperthyroidism).It is caused by an abnormal immune system response that causes the thyroid gland to produce too much thyroid hormones. "The SHB (SH2 domain containing adaptor protein B) region has been identified as hypermethylated in Graves’ disease." (PMID 38785978, 2024).
leukemia (1 paper, 2025). A malignant (clonal) hematologic disorder, involving hematopoietic stem cells and characterized by the presence of primitive or atypical myeloid or lymphoid cells in the bone marrow and the blood. "Concurrently, Jamalpour et al45 reported a network involving SH2 domain-containing adaptor protein B (SHB), B-cell lymphoma 6 corepressor like 1 (BCORL1), and TET1 that enhances lymphoid traits, vascular development, and leukemia cell survival." (PMID 40520993, 2025).
tumor (6 papers, 2016 to 2022). "In tumor cell enriched regions, SHB, VRK2, KRT6A, GRHPR, CGA, SLC6A8, and LY6D were associated with the survival of NPC patients (P < 0.05)." (PMID 36618352, 2022). "SHB has previously been described in contexts of tumor angiogenesis, vascular leakage, myeloid infiltration and T cell responses and we thus considered it appropriate to study the effects of Shb-deficiency in the 4T1 breast carcinoma model." (PMID 29721156, 2018). "In the same study, in HCC sections from patients who underwent curative resection, expression of SHB in HCC tumours was positively correlated with a more aggressive phenotype, namely higher tumour number, loss of tumour encapsulation and a higher TNM stage, and reduced post‐resection survival." (PMID 34846790, 2022). "In tumor biology, absence of SHB aggravates BCR-ABL induced myeloid leukemia, whereas solid tumor growth is reduced due to impaired angiogenesis." (PMID 29721156, 2018).
infection (2 papers, 2020 to 2022). The state of being infected such as from the introduction of a foreign agent such as serum, vaccine, antigenic substance or organism. "ShB resistance has been typically scored on a 0–9 or 1–9 scale by measuring the proportion of the stem above the waterline with signs of infection with 1 being very resistant and 9 being very susceptible." (PMID 32206941, 2020). "Together, these data indicate that YSBR1 is a reliable resistance variety to ShB and is able to suppress R. solani expansion after its initial infection." (PMID 34582620, 2022). "Together, these data demonstrate that R. solani induces rice chlorophyll degradation to facilitate its infection, and suppression of this process improves rice ShB resistance." (PMID 34582620, 2022). "A complication in ShB-resistance genetic mapping studies is that the level of infection shown by a plant is correlated not only with resistance directly interacting with the pathogen but also with plant growth traits, particularly plant height (PH) and heading date (HD)." (PMID 32206941, 2020). "In addition, whether this kind of hyphae behaviour related to ShB resistance still needs further validation using many more varieties as well as the detailed observation of infection structure." (PMID 34582620, 2022).
SHB also shares sentences with these, for which no sentence is quoted: cancer (1 paper); melanoma (1); pheochromocytoma (1).